RBL1 (RB transcriptional corepressor like 1)
Diseases named in the same sentence as RBL1 in open-access papers (continued):
Sharing a sentence is not in itself a finding about the gene and the disease.
glioblastoma (1 paper, 2016). The most malignant astrocytic tumor (WHO grade IV). "Moreover, in a GFAP-CreER; PtenloxP/loxP; Trp53loxP/loxP; Rb1loxP/loxP; Rbl1−/− GEMM model of glioblastoma where tumor can spontaneously arise in different regions of the cerebrum, tumors that arose near the SVZ were more likely to be of proneural subtype (p < 0.0001)." (PMID 27056901, 2016). "To confirm our clinical finding, we tested the distribution of glioblastoma subtypes in a GFAP-CreER; PtenloxP/loxP; Trp53loxP/loxP; Rb1loxP/loxP; Rbl1−/− GEMM model where glioblastoma can arise anywhere in the cerebrum." (PMID 27056901, 2016). "In a GFAP-CreER; PtenloxP/loxP; Trp53loxP/loxP; Rb1loxP/loxP; Rbl1−/− Genetically Modified Murine Model (GEMM) of glioblastoma where tumor can spontaneously arise in different regions of the cerebrum, glioblastoma that arose near the SVZ were more likely to be of proneural subtype." (PMID 27056901, 2016).
hemangioblastoma (1 paper, 2024). "Among these genes, RB transcriptional corepressor like 1 (Rbl1) was found to promote subretinal angiomatous proliferation and hemangioblastoma in mice upon loss." (PMID 38955924, 2024).
malignant glioma (1 paper, 2019). A grade III or grade IV glioma arising from the central nervous system. "As a CNV-driven ceRNA, CDKN2B has been reported to serve as a functional unit in the oncogenesis of malignant gliomas, its ceRNA pairs, CDK2 and RBL1, were also annotated in cell cycle and located in the downstream of the pathway." (PMID 31719831, 2019).
myeloma (1 paper, 2021). "Of the MRs, the specific roles of PRKDC and RBL1 and their regulons in DNA damage/repair would be consistent with supporting the maintenance of MDMS8 myeloma cell’s loss of genetic material." (PMID 34922559, 2021).
neuroendocrine lung tumor (1 paper, 2022).
renal cell carcinoma (1 paper, 2020). "Higher expression of RBL1 was associated with significantly worsened prognosis in renal cell carcinoma (P = 2.5e-06)." (PMID 33041663, 2020).
tumor (92 papers, 2007 to 2025). "It has been demonstrated that 3p107 (RBl1) and 3p130 (RBl2) deletions which are observed in most human SCLCs are particularly associated with tumor progression." (PMID 35620343, 2022). "In addition, it has been recently reported that variants mapping to RBL1 correlated with tumor T cell subset abundance." (PMID 34638509, 2021). "Our data are consistent with those of previous reports that the tumor suppressor properties of the RB1 gene are significantly stronger than those of RBL1 and RBL2 and that among RB family members only RB1 inactivation is commonly found in human cancer." (PMID 36928314, 2023). "Evidence for RB1 mediated tumor suppression is more readily detected across a wider spectrum of tissues and biological contexts while evidence for RBL1 and RBL2 tumor suppressor activity is more restricted." (PMID 35368709, 2022). "The three members of the RB family, RB1, RBL1/p107 and RBL2/p130, are key regulators of the cell cycle and their dysregulation is strongly associated with tumor initiation and progression." (PMID 34638509, 2021). "Conversely, loss of the endogenous CDK4/6 inhibitors (CDKN2A, CDKN2B, CDKN2C, and CDKN2D) or RB-family (RB1, RBL2, and RBL1) are also observed in specific tumor settings, in total the RB-pathway is subject to genetic perturbation in greater than 30% of tumors." (PMID 32242058, 2020). "RBL1 is a tumor suppressor that has the same function as the retinoblastoma 1 (RB1) gene, which involves in cell cycle regulation." (PMID 27779109, 2017). "Retinoblastoma-like 1 (p107/RBL1) is a member of the retinoblastoma gene family (RB), and the genes in this family have been identified as tumor suppressors." (PMID 24694993, 2014). "In conjunction with our findings, the potential inhibitory effects of CD320 on Rbl1, through an unidentified mechanism may also repress tumor vascular growth." (PMID 38955924, 2024). "Multiple studies support the role of RBL1/p107 as a tumor suppressor." (PMID 34638509, 2021). "In conclusion, our study suggested that miR-29b-3p could influence DNA damage response by regulating the expression of DNMT3B, Bcl-2, PI3KR1, AKT2, and RBL1, thereby affecting tumor radioresistance." (PMID 34604239, 2021). "We observed, in some cases, only a single insertion in the rbl1 gene and this may indicate that loss of heterozygosity (LOH) occurred in the tumor." (PMID 27739525, 2016). "By this method, almost universal rb1 and rbl1 INDELs (88% to 100%) could be demonstrated within the neoplasms." (PMID 27739525, 2016). "Thus both Rb1 and Rbl1 have detectable tumor suppressor activity in the skin." (PMID 35368709, 2022). "Retinoblastoma transcriptional corepressor like 1 (RBL1), known for its modulation in the G1/S cell cycle, behaved oppositely and functioned as a tumor suppressor in a GBM model, conflicts of which could come from either the species’ differences or some other regulations unidentified." (PMID 34540896, 2021). "In addition, mutations in CREBBP, EP300, TP73, RBL1, RBL2 and NOTCH family genes are largely mutually exclusive, suggesting that they may play similar tumor-promoting roles in the onset of SCLC." (PMID 34168983, 2021).
tumor (continued). "Finally, gene expression studies revealed that NFs + Sali could upregulate expression of Rbl1 and Rbl2 tumor suppressor genes as well as caspase 3 that can lead to caspase-dependent apoptosis, and simultaneously decreased Wnt signaling pathway." (PMID 29925966, 2018). "The DEPs participated in numerous oncogenic pathways, PI3K/AKT/mTOR cell signaling, and the silencing of several tumor suppressors, such as PTEN and RBL1, during tumorigenesis." (PMID 38672200, 2024). "We first investigated the consequences of repressing retinoblastoma-like 1 (RBL1/p107), a tumor suppressor homologous to retinoblastoma protein (RB)." (PMID 37343560, 2023). "We conclude that RBL1 and RBL2 do have important tumor suppressor activity in some contexts, but RB1 remains the dominant tumor suppressor in the family." (PMID 35368709, 2022). "In the 20 cases analyzed, we detected three fusion events in known cancer driver genes (ATM in LUSC2; PTEN in LUSC1; WHSC1 in LUSC1), and a further seven events in candidate tumor-suppressor genes, including BOD1, DLG2, MBD2, and RBL1." (PMID 30348992, 2019). "HPV E7 is well known to subvert E2F regulation by binding and enhancing the degradation of the RB1 tumor suppressor and the related RBL1 (p107) and RBL2 (p130) proteins as well as through other mechanisms." (PMID 28968467, 2017). "PC3-ML cells contain high levels of exosomal miR-888, which downregulates proteins such as Krüppel-like factor 5 (KLF5), retinoblastoma-like protein 1 (RBL1), tissue Inhibitor of metalloproteinases 2 (TIMP2), and SMAD family member 4 (SMAD4), strengthening tumour cell abilities." (PMID 41465110, 2025). "Enriched in PC3-ML cells, exosomal miR-888 downregulates important proteins such as Krüppel-like factor 5 (KLF5), retinoblastoma-like protein 1 (RBL1), tissue Inhibitor of metalloproteinases 2 (TIMP2), and SMAD family member 4 (SMAD4), enhancing overall tumor cell capabilities." (PMID 40556678, 2025). "A central question in the field is whether the additional genes in this family, RBL1 and RBL2, are important tumor suppressor genes." (PMID 35368709, 2022). "RB proteins restrain the cell cycle and act as tumor suppressors by interacting with the E2F transcription factors and, in the case of RBL2/p130 and RBL1/p107, by binding to the Multivulva class B (MuVB) core to form the transcriptional repressor DREAM (DP, Rb-like, E2F and MuvB) complex." (PMID 34638509, 2021). "In addition to these tumour suppressor genes, PRMT5 also reduces transcription of RB family tumour suppressor genes including RB1, RBL1 and RBL2 in transformed B‐cell lymphocytic leukaemia cell lines." (PMID 33462997, 2021). "All known β-HPV E7 proteins contain canonical LXCXE (L, leucine; C, cysteine; E, glutamate; X, any amino acid)-based binding sites for the retinoblastoma tumor suppressor family of proteins and many have been documented to bind RB1, RBL1 (p107), and RBL2 (p130)." (PMID 29568286, 2018). "Numerous well-known tumor suppressors, including PTEN and RBL1, were downregulated or absent in CT26/SCID tumors." (PMID 38672200, 2024). "For example, PTEN, RBL1, CDKN2AIP, RNASET2A, HINT1, and PARP12 are well-known tumor suppressors and were downregulated or absent in the CT26/SCID tumors." (PMID 38672200, 2024).
cancer (49 papers, 2007 to 2025). A tumor composed of atypical neoplastic, often pleomorphic cells that invade other tissues. "This suggests that disrupting p130–E2F4-mediated repression might be a viable therapeutic approach to restore or enhance RBL1 expression in RB-deficient cancers." (PMID 41155196, 2025). "Reports of cancer derived mutations in the other RB family genes are less common, nevertheless, experimental models of cancer using mice that are deficient for these genes indicate that RBL1 and RBL2 loss can enhance the cancer phenotype in RB1 mutant animals." (PMID 22417103, 2012). "While RBL1 and RBL2 are infrequently mutated in human cancers, RB1 mutations are prevalent across various cancer types, such as retinoblastoma, osteosarcoma, pinealoma, and melanoma." (PMID 38672640, 2024). "For most cancers the frequency of debilitating RB1 alterations is greater than the frequency of RBL1 or RBL2 alterations." (PMID 35368709, 2022). "While the mutation frequency in RB1 is typically greater than for RBL1 or RBL2, there are some cancer subtypes where this is reversed." (PMID 35368709, 2022). "Yet, this patient also showed a VUS with a high score for pathogenic prediction in the RBL1 gene and a truncating VUS in the PCM1 gene, which are both cancer-related genes." (PMID 36077770, 2022). "Survival analysis showed that hypermethylation of TFDP2, RBL1, and MYBL2 was associated with poor survival in most cancers." (PMID 35664326, 2022). "Meanwhile, survival analysis showed that hypermethylation of TFDP2, RBL1, and MYBL2 was associated with poor survival in most cancers." (PMID 35664326, 2022). "It is noteworthy that alteration of the other pocket protein paralogues RBL1 and RBL2 is rare in both prostate adenocarcinoma and NEPC, suggesting loss of RB1 has a unique role in cancer lineage plasticity in the prostate." (PMID 35368709, 2022). "Transcription of proteins essential for G1-S depends on E2F1-5 proteins and their dimerization partners (pRb, p107, and p130, encoded by RB1, RBL1, and RBL2 respectively); genes encoding these proteins are often dysregulated or mutated in cancer." (PMID 29725503, 2018). "The series of results suggest that low expression of RBL1 account for the radioresistance of 3D carcinoma cells." (PMID 27779109, 2017). "Moreover, the transcripts of the following notional cancer genes were significantly increased: Rbl1, Bcl2l11, Map3k2, Bcl6, Ppp1, Cdc42, and Ppp2." (PMID 38731901, 2024). "For example, the fraction of cancers exhibiting gene deletions versus other genetic alterations is generally higher for RB1 than for RBL1 or RBL2, suggesting selective pressure may favor complete functional inactivation of RB1 alleles." (PMID 35368709, 2022). "The retinoblastoma protein family consists of three proteins (pRB, p107 and p130; also known as RB1, Retinoblastoma-like 1 and Retinoblastoma-like 2 (RBL1-2), respectively) that share significant homology, yet only pRb is found frequently mutated in cancer." (PMID 35663332, 2022). "Since the expression of RBL1 protein was regulated depending on the promotor methylation and was lower in 3D cells when compared with 2D cells, we speculate that RBL1 may play an important role in the radioresistance induction for 3D cultured carcinoma cells." (PMID 27779109, 2017). "Among the RNA targets that displayed a polysomal shift are mRNAs encoding proteins related to cancer, such as NRAS, the Ras-related protein R-Ras2, and those related to cell cycle, such as CDC27, the retinoblastoma binding protein RBBP8, and retinoblastoma-like 1 (RBL1)." (PMID 24842991, 2014). "Similarly, RB1/RBL1/RBL2 can be deleted in cancers, which leads to increased E2F activity." (PMID 38678032, 2024). "We speculate that RBL1 participates in cell cycle regulation downstream of FoxO signaling and thus by pass the inhibition by Sunitinib and Cabozantinib, both of which were shown to mediate cell cycle arrest as the cancer-intrinsic mechanism." (PMID 33041663, 2020).
cancer (continued). "The pattern of RBL1 and RBL2 genetic alteration across cancer types is generally more similar to each other than to RB1, consistent with structural similarities between the paralogues." (PMID 35368709, 2022). "The expression levels of MYBL2, RBL1, LIN9, and E2F5 in various cancers were significantly upregulated." (PMID 35664326, 2022). "In some cancer types like sarcoma, this discrepancy is marked (RB1 = 25%, RBL1 = 0.4%, RBL2 = 2%)." (PMID 35368709, 2022). "Gene array profiles showed that the genes related to antiproliferative pathway were upregulated, such as GTP-binding RAS-like 3 (DIRAS3), retinoblastoma-like 1 (Rbl-1), and cyclin-dependent kinase inhibitor 2B transcript (CDKN2B), but different genes were modulated in various cancer cell lines." (PMID 28377788, 2017). "RBL1 and RBL2 genetic alterations are not common in these neuroendocrine cancers, again indicating RB1 alteration has a unique role in this cancer context." (PMID 35368709, 2022).
infection (2 papers, 2022 to 2024). The state of being infected such as from the introduction of a foreign agent such as serum, vaccine, antigenic substance or organism. "Mouse groups receiving PBS (G-I) plus adjuvant or the ricin B-domain RBL1 [t3490, (G-II)] plus adjuvant showed a modest decrease body weight after challenge infection but had to be euthanized on days 6 and 5, respectively, because of severe illness manifested by lethargy and inability to feed/drink." (PMID 35837473, 2022). "NN1172-infection leads to the down-regulation of many genes related to cell cycle and DNA replication genes, including MCM 2 ~ 6, CDK1 ~ 2, CCNB2, ANAPC2, MAD2L1, WEE1, RBL1, RB1." (PMID 38362295, 2024).
RBL1 also shares sentences with these, for which no sentence is quoted: cervical carcinoma (7 papers); adenocarcinoma (3); hepatocellular carcinoma (3); Retinal dysplasia (3); breast tumor (2); endometrial cancer (2); renal carcinoma (2); acute pancreatitis (1); Arthritis (1); B-cell lymphoma (1); brain tumors (1); COVID-19 (1); Cyanosis (1); Endometrial Cyst (1); Fanconi anemia (1); growth deficiency (1); HCMV infection (1); heart failure (1); lung adenocarcinoma (1); mesothelioma (1); Multiple Organ Failure (1); non-Hodgkin lymphoma (1); Obesity (1); osteosarcoma (1); ovarian carcinoma (1); ovarian leiomyosarcomas (1); pancreatic cancer (1); pericardial effusion (1); prion disease (1); prostate adenocarcinoma (1).
A further 4 diseases each share a sentence with RBL1 in 1 paper.